LIMS1 (LIM zinc finger domain containing 1)
Description:
Within the IPP (ILK-PINCH-PARVIN) complex, binds to F-actin, promoting F-actin bundling, a process required to generate force for actin cytoskeleton reorganization and subsequent dynamic cell adhesion events such as cell spreading and migration.
Synonyms: PINCH-1; PINCH; PINCH1
Tractability: Antibody: UniProt places it where antibodies can reach, with medium confidence; its Gene Ontology location is reachable by antibodies, with medium confidence. PROTAC: ubiquitination databases record sites on it; its protein half-life has been measured.
Gene: Protein-coding gene on chromosome 2 (108,533,671 to 108,687,246, forward strand). Ensembl gene ENSG00000169756.
Subcellular location: Cell junction, focal adhesion; Cell membrane
Subcellular location (Human Protein Atlas): Cytosol; Focal adhesion sites
Pathways (Reactome):
Cell-Cell communication: Cell-extracellular matrix interactions; Regulation of cytoskeletal remodeling and cell spreading by IPP complex components
Gene Ontology:
Molecular function: protein binding; protein kinase binding; zinc ion binding
Biological process: actin filament bundle assembly; actin filament network formation; cell-matrix adhesion; cellular response to transforming growth factor beta stimulus; negative regulation of DNA-templated transcription; positive regulation of canonical NF-kappaB signal transduction; tumor necrosis factor-mediated signaling pathway; cell-cell adhesion; cell-cell junction organization; positive regulation of integrin-mediated signaling pathway; positive regulation of signal transduction
Cellular component: cell-cell junction; focal adhesion; perinuclear region of cytoplasm; cytoplasm; cytosol; plasma membrane
Genetic constraint (gnomAD): Loss-of-function variants: 12 observed, 22.43 expected, observed/expected ratio (o/e) 0.54, 90% interval 0.34 to 0.87. The upper end of that interval is the gene's LOEUF score, 0.87, which puts it in group 3 of 6, group 1 being the genes least tolerant of losing a copy. Missense variants: 111 observed, 219.23 expected, observed/expected ratio (o/e) 0.51, 90% interval 0.43 to 0.59. Synonymous variants: 57 observed, 69.86 expected, observed/expected ratio (o/e) 0.82, 90% interval 0.66 to 1.02.
Homologues: Orthologues: tropical clawed frog lims1 (94% identical), zebrafish lims1 (94% identical), pig LIMS1 (80% identical), zebrafish lims2 (77% identical), Drosophila melanogaster stck (65% identical), Caenorhabditis elegans unc-97 (58% identical), Caenorhabditis elegans pin-2 (37% identical), Drosophila melanogaster Zasp67 (21% identical). Paralogues in human: LIMS3 (91% identical), LIMS4 (91% identical), LIMS2 (83% identical).
Diseases named in the same sentence as LIMS1 in open-access papers:
LIMS1 is named in the same sentence as 67 diseases in open-access papers, as found by Europe PMC text mining. Sharing a sentence is not in itself a finding about the gene and the disease. The quoted sentences say what the papers report.
breast cancer (5 papers, 2019 to 2023). A primary or metastatic malignant neoplasm involving the breast. "For instance, a high level of LIMS1 promoted tumor progression in breast cancer, and the LIMS1–myoferlin signaling axis may contribute to this process." (PMID 36901953, 2023). "Also, during the knockdown of LIMS1, apoptosis was induced in breast cancer cells." (PMID 33048956, 2020).
lung adenocarcinoma (4 papers, 2020 to 2023). A carcinoma that arises from the lung and is characterized by the presence of malignant glandular epithelial cells. "The LIMS1 protein was strongly expressed in tumor tissues among six patients with NSCLC (three with lung adenocarcinoma and three with lung squamous cell carcinoma)." (PMID 36901953, 2023). "For instance, Guo and colleagues showed that DRP1 is repressed by LIM Zinc Finger Domain Containing 1 (PINCH-1) in lung adenocarcinoma." (PMID 33233365, 2020).
neuroblastoma (4 papers, 2013 to 2020). Neuroblastoma (NB) is the most common solid, extracranial childhood tumor. "Inhibition of LIMS1 through knockdown of LIMS1 can inhibit cell proliferation of neuroblastoma cells." (PMID 33195283, 2020). "One study using neuroblastoma cell lines found that silencing the LIMS1/ILK pathway reduced cellular proliferation, highlighting its potential as a therapeutic target." (PMID 33048956, 2020).
pancreatic cancer (4 papers, 2020 to 2023). "Increased LIMS1 (LIM and senescent cell antigen-like-containing domain protein 1), a focal adhesion protein, has been associated with poor prognosis in laryngeal and pancreatic cancers." (PMID 33048956, 2020). "The LIM and senescent cell antigen-like domain 1 (LIMS1), a member of PINCH, was positively associated with advanced TNM stage and poor prognosis of patients with pancreatic cancer and promoted cancer cell survival in the oxygen-glucose-deprived TME." (PMID 36901953, 2023). "LIMS1 functions as an oncogene to promote the survival of pancreatic cancer cells under oxygen–glucose deprivation conditions." (PMID 33195283, 2020).
heart failure (3 papers, 2011 to 2016). Inability of the heart to pump blood at an adequate rate to meet tissue metabolic requirements. "Specifically, Lims1 is required for normal development of cranial and cardiac neural crest-derived structures and mice double knockout for Lims1 and 2 develop dilated cardiomyopathy and die of heart failure within 4 weeks." (PMID 27604219, 2016). "Double inactivation of LIMS1 and 2 leads to the development of heart failure and fibrosis in mice." (PMID 27983601, 2016).
laryngeal carcinoma (3 papers, 2018 to 2020). Carcinoma that arises from the laryngeal epithelium. "High expression of LIMS1 is associated with poor prognosis in human laryngeal carcinomas." (PMID 33195283, 2020).
colon cancer (2 papers, 2006 to 2024). "The discernments delineate RBMS3 as a novel suppressor of cancer via LIMS1, thereby bestowing fresh therapeutic possibilities and illuminating the intricacies of colon cancer." (PMID 38618967, 2024). "Our research has unequivocally demonstrated that increased expression of LIMS1 impedes the progression of colon cancer, whereas LIMS1 knockdown yields the opposite effect." (PMID 38618967, 2024). "Subsequently, we conducted MTT, EDU, Transwell assays, and scratch assays to assess the influence of LIMS1 on cell proliferation, migration, and invasion in colon cancer cells." (PMID 38618967, 2024). "The investigation ascertained that RBMS3 inhibits the progression of colon cancer by regulating LIMS1." (PMID 38618967, 2024). "In order to gauge the impact of LIMS1 on colon cancer cells, we established overexpressed and knockdown cell lines for LIMS1 in HCT116 and HCT15." (PMID 38618967, 2024). "Overall, these findings strongly indicate that RBMS3 impedes the progression of colon cancer by governing the stability of LIMS1." (PMID 38618967, 2024). "The effect of RBMS3 and LIM zinc finger domain 1 (LIMS1) on colon cancer was substantiated via animal models and cellular experiments." (PMID 38618967, 2024). "Our investigations uncovered that the expression of LIMS1 significantly hindered the proliferation of colon cancer cells, while its knockdown notably accelerated proliferation." (PMID 38618967, 2024). "RBMS3 enhances the mRNA stability of LIMS1, which, in turn, impedes the proliferation, migration, and invasion of colon cancer cells." (PMID 38618967, 2024). "We establish that RBMS3 regulates the mRNA stability of LIMS1, consequently modulating LIMS1's expression level and impeding colon cancer progression." (PMID 38618967, 2024). "Serving as a potential inhibitor of colon cancer cell proliferation, migration, and invasion, RBMS3 modulates the mRNA stability of LIMS1, thereby exerting a suppressive influence on the advancement of colon cancer." (PMID 38618967, 2024). "Subsequently, we conducted MTT and Transwell migration experiments to investigate whether the downregulation of LIMS1 could counteract the inhibitory effects induced by RBMS3 overexpression on colon cancer cells." (PMID 38618967, 2024). "Furthermore, the results from the Transwell assay and scratch assay showed the expression of LIMS1 reduced the migration and invasion of colon cancer cells." (PMID 38618967, 2024). "Consequently, our findings propose that LIMS1 might fulfill distinct molecular roles in colon cancer cells versus stromal cells." (PMID 38618967, 2024). "Furthermore, our study has unveiled the mechanistic involvement of RBMS3, acting as a tumor suppressor, in regulating the mRNA stability of LIMS1, thereby influencing its expression level and consequently restoring LIMS1's inhibitory impact on colon cancer cells." (PMID 38618967, 2024). "Lastly, we assessed the impact of altered RBMS3 expression on LIMS1 mRNA stability in colon cancer cells treated with Actinomycin D, revealing that RBMS3 amplified the stability of LIMS1 mRNA." (PMID 38618967, 2024). "Furthermore, our study has ascertained that alterations in RBMS3 expression have the ability to impact the stability of LIMS1 mRNA stability, thereby signifying LIMS1's pivotal role as a target gene of RBMS3 in colon cancer." (PMID 38618967, 2024).
congenital heart disease (2 papers, 2018 to 2019). A heart disease that is present at birth. "LIMS1 (also called PINCH1) has been suggested to be associated with left‐sided congenital heart disease." (PMID 29928570, 2018). "In addition, considering the role of macrophages in resistance to virus infections, LIMS1 might also represent a link of intrauterine virus infections and congenital heart disease." (PMID 31552105, 2019).
epilepsy (2 papers, 2020 to 2023). A brain disorder characterized by episodes of abnormally increased neuronal discharge resulting in transient episodes of sensory or motor neurological dysfunction, or psychic dysfunction.
gastric cancer (2 papers, 2021 to 2025). A primary or metastatic malignant neoplasm involving the stomach. "The results of western blot and quantitative real-time PCR showed that the NME2 knockdown significantly downregulated the expression levels of RIPK1, STARD5, and LIMS1 in gastric cancer stem-like cells from human solid tumors." (PMID 34628473, 2021). "Collectively, NME2 was critical for the maintenance of stemness of gastric cancer stem-like cells via promoting the expression of stemness-associated transcriptional factors (c-Myc, LGR5, ALDH1, and Nanog) and anti-apoptosis genes (RIPK1, STARD5, and LIMS1)." (PMID 34628473, 2021).
glioblastoma (2 papers, 2009 to 2015). The most malignant astrocytic tumor (WHO grade IV). "Importantly, PRCP, PTRF, LIMS1 and FSTL1 were expressed in the developing murine brain vasculature and are also overexpressed in glioblastoma, suggesting a role in tumor angiogenesis." (PMID 19924294, 2009). "The exact role of other vascular genes such as PRCP, LIMS1 and ENC1 in glioblastoma is not clear yet, but given their expression pattern, an implication in tumor angiogenesis is possible and merits further investigation." (PMID 19924294, 2009).
skin cancer (2 papers, 2022 to 2023). "In skin cancer, LIMS1–neural precursor cells expressed a developmentally downregulated protein 4-insulin-like growth factor-1 receptor signaling axis, which is critical for promoting skin cancer cell proliferation and survival." (PMID 36901953, 2023).
Aleutian disease (1 paper, 2024). "From this, we identified several candidate genes contributing to the growth and feed efficiency (ARID1B, APPL1, TOX, and GPC5), reproduction (GRM1, RNASE10, WNT3, WNT3A, and WNT9B), pelt quality (MYO10, and LIMS1), and Aleutian disease tests (IFNGR2, APEX1, UBE3A, and STX11)." (PMID 38167844, 2024).
and acute leukemia (1 paper, 2013). "Among these overlapped regions, several functional genes were found, including LIM and senescent cell antigen-like domains 1 (LIMS1), myosin light chain kinase family, member 4 (MYLK4), frizzled family receptor 6 (FZD6), and brain and acute leukemia, cytoplasmic (BAALC)." (PMID 23390598, 2013).
autoimmune disorder (1 paper, 2024). "Previous studies have reported its involvement in kidney allograft rejection, an autoimmune disorder resulting from hypoxia-induced upregulation of the LIMS1 antigen in human kidney cells." (PMID 38729610, 2024).
Hirsutism (1 paper, 2018). Abnormally increased hair growth referring to a male pattern of body hair (androgenic hair). "In addition to validation of SNPs associated with these previous traits, our study identified three novel hirsutism loci that were also eQTLs for BCL2, GCC2 and LIMS1, and TBX15." (PMID 29895819, 2018).
kidney transplant (1 paper, 2023). A surgical procedure in which one or both kidneys from a donor are implanted into a recipient. "In summary, we confirmed and extended prior data regarding the LIMS1 locus implicated in kidney transplant rejection, and specifically the D-R mismatch at the CNV-tagging SNP rs893403, and identified its association with DCGL." (PMID 37676733, 2023).
lipoma (1 paper, 2025). A benign, usually painless, well-circumscribed lipomatous tumor composed of adipose tissue. "LIMS1, located downstream of hsa_circ_0000994, encodes a LIM domain-containing protein and is a known translocation partner in lipoma." (PMID 40949879, 2025).
macular degeneration (1 paper, 2024). Loss of vision in the central portion of the retina (macula), secondary to retinal degeneration. "Therefore, the disruption of the oBRB by the anti-LIMS1 autoantibody may cause the deterioration in the microenvironment of the photoreceptor layer, resulting in macular degeneration in eyes with pathologic myopia." (PMID 38729610, 2024).
Myocardial fibrosis (1 paper, 2024). "Of the other genes that had significant association with myocardial fibrosis, LIMS1, TLR3 and PLB1 had heart enhanced interactions." (PMID 38848015, 2024).
myopia (1 paper, 2024). "Our study demonstrates that the serum anti-LIMS1 autoantibody is a potential biomarker for pathologic myopia, indicated by its close association with the grades of MMD." (PMID 38729610, 2024). "We found that anti-LIMS1 autoantibody could distinguish high myopia from emmetropia, which was also associated with MMD grades." (PMID 38729610, 2024). "The IgG subclasses of the anti-LIMS1 autoantibody in pathologic myopia were predominantly IgG1/IgG2/IgG3 (ANOVA, all p < 0.0001)." (PMID 38729610, 2024). "The ROC analysis showed that, when the signal intensity of anti-LIMS1 autoantibody was used to identify high myopia, the AUC was 0.697 and the cut-off value was 8.42, with 40.1% sensitivity and 90.0% specificity." (PMID 38729610, 2024). "An unbiased human proteome array followed by a customized focused microarray identified serum anti-LIMS1 autoantibody as the high myopia-related autoantibody." (PMID 38729610, 2024). "When the signal intensity of anti-LIMS1 autoantibody was used to identify pathologic myopia, the ROC analysis showed that the AUC was 0.762, with a cut-off value of 9.03, reaching 51.7% sensitivity and 90.7% specificity." (PMID 38729610, 2024). "•Serum anti-LIMS1 autoantibody as a potential biomarker for pathologic myopia." (PMID 38729610, 2024). "After the identification of the circulating anti-LIMS1 autoantibody as a pathologic myopia-related autoantibody, we investigated whether the LIMS1 antigen was expressed in the human eye." (PMID 38729610, 2024). "With proteomic tools, we have shown that the serum level of the anti-LIMS1 autoantibody is significantly increased in pathologic myopia and is a potential serum biomarker for this disease, supporting a previously unrecognized autoimmune aspect of the pathogenesis of pathologic myopia." (PMID 38729610, 2024). "It is noteworthy that even in patients at the earliest stage of pathologic myopia, that is MMD grade 2, the serum level of the anti-LIMS1 autoantibody is already clearly elevated, supporting its future clinical utility as an early biomarker of pathologic myopia." (PMID 38729610, 2024). "In addition to the correlation between the anti-LIMS1 autoantibody and AL, we investigated its potential relationship with MMD, a typical complication of pathologic myopia." (PMID 38729610, 2024).
myopic macular degeneration (1 paper, 2025). "Moreover, it has been documented that serum concentrations of anti-LIM and senescent cell antigen-like-containing domain protein 1 (anti-LIMS1) autoantibodies were markedly increased and significantly associated with the severity of myopic macular degeneration." (PMID 40909333, 2025).
osteosarcoma (1 paper, 2020). A usually aggressive malignant bone-forming mesenchymal neoplasm, predominantly affecting adolescents and young adults. "Furthermore, AMN1 and ZP3 may be protective factors in osteosarcoma (HR: 1.26e−36 and 1.13e−07, respectively), whereas LIMS1, SAMD4A, and SPARC appear to be harmful factors in this setting (HR: 699.2, 167, and 298.7, respectively)." (PMID 33195283, 2020). "Thus, LIMS1 may be considered as a biomarker for osteosarcoma." (PMID 33195283, 2020).
pathologic myopia (1 paper, 2024). "We further explored the antibody classes and subclasses of the anti-LIMS1 autoantibody in pathologic myopia." (PMID 38729610, 2024). "The treatment of RPE cells with IgG extracted from the sera of patients with pathologic myopia significantly impaired their barrier function, whereas the depletion of the anti-LIMS1 autoantibody attenuated this effect." (PMID 38729610, 2024). "Therefore, the anti-LIMS1 autoantibody is likely to be related to pathologic myopia-related autoantibody." (PMID 38729610, 2024). "Different subtypes of autoantibody play distinct roles in the autoimmune process, and the predominant subclasses of the serum anti-LIMS1 autoantibody identified in pathologic myopia (IgG1/IgG2/IgG3) could provide further clues to the possible autoimmune responses involved in this disease." (PMID 38729610, 2024).
Sepsis (1 paper, 2025). Sepsis is defined as life-threatening organ dysfunction caused by a dysregulated host response to infection. "In rAAV-sh-controls, sepsis induced upregulation across TA and EDL muscle of Ilk1 and Fermt2 and integrin-receptor-complex-related genes Itga7, ItgB1, Tln1, Lims1, Lims2, Parva (P < 0.001), whereas in SOL muscle Lims1, Lims2 and Fermt2 were not and Vcl1 (P < 0.001) was upregulated." (PMID 41385533, 2025).
uveitis (1 paper, 2024). An inflammatory process affecting a part of or the entire uvea. "Further investigation suggested that the anti-LIMS1 autoantibody also induces a pro-inflammatory state in RPE cells and triggers the release of pro-inflammatory mediators, which is similar to the autoimmune pathogenesis of uveitis." (PMID 38729610, 2024).